TNF (tumor necrosis factor)
Diseases named in the same sentence as TNF in open-access papers (continued):
Sharing a sentence is not in itself a finding about the gene and the disease.
periodontitis (continued). "Importantly, TNF‐α protein levels remained significantly lower in both JAK inhibitor‐treated groups, similar to the control group, indicating that JAK inhibition prevented the increase in TNF‐α protein expression induced by experimental periodontitis." (PMID 41041963, 2025). "This study aimed to evaluate the association between periodontitis stage and grade with systemic levels of C-reactive protein (CRP), interleukin-1β (IL-1β), interleukin-6 (IL-6), and tumor necrosis factor-alpha (TNF-α) and assess changes following standardized non-surgical periodontal therapy." (PMID 41440349, 2025). "However, diabetic monocytes exposed to P. gingivalis LPS secreted significantly more TNFα than non-diabetics, especially in severe periodontitis cases, suggesting a hyperinflammatory monocytic phenotype linked to disease severity." (PMID 41280935, 2025). "IL-17 acts synergistically with TNF-α and IL-1 to induce the release of receptor activator of nuclear factor-kappa B ligand (RANKL), which binds to the receptor RANK on the surface of preosteoclasts, promoting osteoclastogenesis and initiating the process of bone destruction in periodontitis." (PMID 40077138, 2025). "Hence, the present study aimed to assess the clinico-radiographic parameters as well as salivary levels of RANKL, OPG, IL-6, and TNF-α around standard implants- and SDI-supported fixed partial dentures in partially dentate type-2 diabetes mellitus (T2DM) patients treated for periodontitis." (PMID 39625348, 2024). "In addition, lipid peroxidation markers (LPO) and cytokines (TNF-α, IL-6, and IL-10) in the gingival crevicular fluid were significantly elevated in T2DM patients with periodontitis compared to systemically healthy controls with periodontitis." (PMID 39337292, 2024). "Periodontitis patients have significantly elevated levels of LY96, which leads to the formation of LY96-TLR4-CD14 complexes that trigger the myeloid differentiation factor-88 (MyD88) pathway, resulting in TNF-α, IL-6, IL-8, and IL-2 production in the gingival tissue." (PMID 39555084, 2024). "The molecular docking results showed that BBR can effectively bind to periodontitis targets ALOX5, AKT1, NOS2, and TNF, indicating that these four targets have high biological activity and can serve as potential biomarkers and key therapeutic targets for BBR treatment of periodontitis." (PMID 38704553, 2024). "Moreover, the study found that in the chronic periodontitis group of T2DM, there was a significant difference in the serum level of miR-200b, which was significantly negatively correlated with IL-10 and positively correlated with TNF-α." (PMID 37664859, 2023). "Analyses performed after 4 weeks showed that animals with induced periodontitis and not treated with cocoa had significantly higher serum levels of TNF-α compared to animals in the control group (healthy animals) and animals with induced periodontitis that were treated with cocoa." (PMID 37764711, 2023). "From there, the inflammatory response during periodontitis has been shown to be marked by the local release of specific proinflammatory mediators and enzymes, including C-reactive protein (CRP); metalloproteinases (MMPs); interleukin- (IL-) 1β, IL-6, and IL-10; and tumor necrosis factor (TNF-α)." (PMID 37214190, 2023). "CD14+ monocytes secrete a variety of cytokines, including TNF-α, IL-1β, IL-6, IL-8, CCL2, CCL3, and CCL5, compared to CD14− cells from GCF in patients with periodontitis, which suggests that CD14+ monocytes may be a source of CCL5 in GCF and gingival tissue in patients with periodontitis." (PMID 38139161, 2023). "Furthermore, solo hDPMSC injections had no efficacy on TNF-α levels when compared to the periodontitis group." (PMID 40226401, 2023).
periodontitis (continued). "Furthermore, periodontitis worsens systemic inflammation, leading to the release of pro-inflammatory cytokines and tissue-damaging agents into the circulatory system, such as IL-1β, IL-10, IL-17, Th17, IFN-gamma, GM-CSF, G-CSF, IL-8, TNF-α, and MCP1." (PMID 37892006, 2023). "In addition, our ligature-induced model confirmed the distinguished bone resorption and the pro-inflammatory gene expression of IL-1β, TNF-α, CCL-2, Nos2, IL-17 and IL-6, which were highly enhanced during the progress of the early acute phase of new periodontitis." (PMID 38069063, 2023). "Moreover, Machado and colleagues showed significantly higher TNF-α and IL-6 levels among pregnant women with periodontitis compared to healthy non-pregnant controls." (PMID 36432584, 2022). "Then, the treatment of periodontitis with multi-dose SHED every 7 days can change the expression profile of cytokines in gingival crevicular fluid, with a reduction in the pro-inflammatory cytokines TNF-α, IFN-γ and IL-2, and an increase in the anti-inflammatory molecule IL-10." (PMID 34868054, 2021). "Pro-inflammatory cytokines, such as tumor necrosis factor (TNF-α) and interlukin (IL-6) directly, and indirectly activated osteoclast differentiation through receptor activator of nuclear factor-κB ligand (RANKL)/RANK pathway and induced alveolar bone resorption in periodontitis." (PMID 33498415, 2021). "A clinical control trial showed that periodontitis patients with concurrent IBD treated with anti-tumor necrosis factor alpha (anti-TNF-α) therapy had a higher probability of healing than did those managed without anti-TNF-α therapy." (PMID 34616755, 2021). "In the other part, periodontitis, through bacteria or their virulence factor translocation, act like a constant challenge to immune inflammatory cells, increasing the release of pro-inflammatory mediators (CRP, TNF-α, IL-6, and IL-1β) and periodontal-derived EVs into circulation." (PMID 34769262, 2021). "Unlike those from healthy individuals, OBMC-derived supernatants from periodontitis patients exhibited decreased ability to induce secretion of IFN-γ by allogeneic healthy PBMCs treated with IL-2, while they triggered significant levels of TNF-α, IL-1β and IL-6 by untreated PBMCs." (PMID 33672708, 2021). "The level of TNF-α was not significantly changed according to periodontitis status." (PMID 34199256, 2021). "The level of circulatory TNF-α in non-smoking patients with chronic periodontitis was found to be closely related to the percentage of PD > 7 mm (r = −0.41 and p = 0.04) at baseline, but the correlation coefficient was reversed to 0.32 (p < 0.001) after subgingival scaling." (PMID 34299815, 2021). "Moreover, the DNA methylation status of the TNF gene promoter was almost stable in normal sites in periodontitis patients throughout the evaluation period and was not restored after periodontal therapy to that of healthy patients." (PMID 32867386, 2020). "Even in RA patients without periodontitis anti-TNF resulted in an increase of GI." (PMID 33193432, 2020). "In addition, diabetic status upregulates monocytic TNF-α secretion (4.6-fold increase) of periodontitis patients in the presence of Gram-negative bacterial challenge." (PMID 32089705, 2020). "Therefore, the main objective of this study was to analyze the levels of visfatin, IL-6, and TNF-α in obese and non-obese individuals, with or without generalized chronic periodontitis (GCP)." (PMID 31365708, 2019). "Similar to these studies, our data demonstrated the down-regulation of pro-inflammatory cytokines (TNFα, IL-17, and IL-6) using cytokine cocktail-treated compared with non-cytokine-treated ADMPC, which have been reported to be involved in various inflammatory diseases, including periodontitis." (PMID 30696909, 2019).
periodontitis (continued). "Indeed, both of TNF-α and IL-8 levels in the gingival crevicular fluids of HD patients with periodontitis were reportedly not significantly different compared to patients with gingivitis (p = 0.213 and 0.823, respectively)." (PMID 31382656, 2019). "Numerous reports have shown that periodontitis could raise the serum pro-inflammatory state, characterized by increased levels of C Reactive Protein (CRP) and pro-inflammatory cytokines (e.g. TNF-α), and decreased levels of anti-inflammatory markers (e.g. IL-10)." (PMID 29422938, 2018). "Second, involvement of those cells in periodontal tissue as source of RANKL could not be excluded in TNF-α-mediated osteoclast formation of the type 1 diabetes with periodontitis." (PMID 29240821, 2017). "In conclusion, periodontitis in the asthmatic mice reduced the inflammatory migrated cells in the BAL (eosinophils, lymphocytes, macrophages), as well as in reduce the levels of the IL-4 and TNF-α cytokines, which was additionally accompanied by a decreased mucus production." (PMID 29145431, 2017). "The question rises here is that whether these biomarkers (TNF-α and IL-1α) can have relationship with success rate of non-surgical treatment for chronic periodontitis." (PMID 29238418, 2017). "Moreover, the fact that TNF-α and IL-6 are produced in the adipose tissues could also support the shared link between obesity, T2DM, and periodontitis." (PMID 26339142, 2015). "Consistent with previous studies, our results demonstrate that LPS upregulates IL-1, IL-6, and TNF-α gene expression in hPDLCs, whereas pretreatment with PTL effectively inhibits the production of these cytokines, thus indicating the anti-inflammatory potential of PTL in treatment of periodontitis." (PMID 25610476, 2014). "Thus, considering all the GCF samples (from periodontitis patients and controls), the percentage of samples considered below the detection level were 13% for IL-1β, 31% for IL-6, 3% for IL-10 and 5% for TNF-α (data not shown)." (PMID 24944641, 2014). "We suggest that the strong HtrA1 positivity observed in plasma cells of tissues from patients affected by chronic and aggressive periodontitis could reduce the inhibitory effects of TGF-β, allowing the increase of inflammatory mediators (TNF-α; IL-1β) promoting disease progression." (PMID 24979214, 2014). "The aftermath of inflammatory progression of periodontitis systemically leads to production of mediators in the vicinity such as C-reactive protein (CRP), interleukins-1beta (IL-1β), tumor necrosis factor-alpha (TNF-α) and interleukin 6 (IL-6) i.e Proinflammatory cytokines." (PMID 24198887, 2013). "Interestingly, in individuals with stable coronary artery disease and with chronic periodontitis, nonsurgical periodontal therapy decreased serum levels of TNF‐α, IL‐6 and CRP, which could help to reduce the inflammatory burden in these individuals." (PMID 39494478, 2024). "In addition, this study found that there was no significant improvement in IL-1β and TNF-α in periodontitis patients after NSPT, which may be related to the small sample size." (PMID 38877442, 2024). "Thus, inflammatory mediators such as C-reactive protein (CRP), tumor necrosis factor -α (TNF-α) and interleukin-6 (IL-6) may be the link between periodontitis and hypertension, and smoking may promote the co-occurrence and development of the two diseases as a common risk factor." (PMID 37308938, 2023). "Therefore, sTNF-R1 and sTNF-R2 in saliva may be increased by oral inflammatory diseases, including periodontitis, which may act to modulate salivary TNF-α at low levels, but not at relatively high levels." (PMID 35200250, 2022). "Interestingly, Zuomin Wang reported that, relative to that of the control group, the mRNA expression level of cytokines TNF-α in the lung tissue of the ligature plus P. gingivalis-induced periodontitis groups increased significantly at 8 weeks but otherwise not obviously at 2 weeks." (PMID 36060644, 2022).
periodontitis (continued). "However, these substances raise IOP rather than lower it, and the production of TNF-α during periodontitis blocks insulin receptors and may contribute to an adverse effect on the control of type 2 diabetes." (PMID 35028240, 2022). "Indeed, the augmentation of systemic markers due to periodontitis, such as specific interleukins, fibrinogen, albumin, CRP, matrix metalloproteinase-9 or tumor necrosis factor-α, participate to the vascular endothelial weakening and its dysfunction and, therefore, can promote systemic diseases." (PMID 35096635, 2021). "Indeed, epidemiologic studies have shown that C‐reactive protein, which is synthesized in hepatocytes and activated by proinflammatory cytokines, including tumor necrosis factor alpha and IL‐6, is a modifying factor of periodontitis and nonalcoholic fatty liver disease." (PMID 34463983, 2021). "Studies suggest that inflammation in periodontal tissues due to periodontitis increases secretion of different inflammatory cytokines, notably interleukin B (IL-1β), interleukin IL-6, interleukin 8 (IL-8), interleukin 17 (IL-17), and tumor necrosis factors alpha (TNF-α)." (PMID 33711951, 2021). "Of particular interest, in periodontitis patients, IL-36γ mRNA is positively correlated with archetypal inflammatory cytokines already known to be involved in periodontitis and inflammatory diseases, i.e., IL-1β, IL-6, TNF-α and IL-17A while IL-36β or IL-36Ra are not correlated with these cytokines." (PMID 31848404, 2019). "While it has been suggested that IL-36γ, like other inflammatory cytokines including TNF-α and IL-33, may support osteoclastogenesis by enhancing the RANKL/OPG ratio, its role in the alveolar bone loss associated with periodontitis has not yet been investigated." (PMID 31848404, 2019). "Interestingly, elevated salivary levels of pro-inflammatory cytokines including Tumor Necrosis Factor (TNF)-α and Interleukin (IL)-1β and molecules involved in tissue degradation such as Matrix Metalloproteinase (MMP)-8 and -9 has been reported in saliva from patients with periodontitis." (PMID 26799067, 2016). "Significant reductions in gingival crevicular fluid (GCF) TNF-α and IL-10 levels have been observed following non-surgical periodontal therapy (NSPT) in Stage III Grade B periodontitis." (PMID 41440349, 2025). "This study aimed to compare endocan levels in individuals with periodontitis both before and after non-surgical periodontal therapy (NSPT) by analyzing the interaction between the proinflammatory mediator TNF-α and the angiogenic factor VEGF-A." (PMID 40426985, 2025). "The difference in change of TNF-α levels between smokers and non-smokers following step IV therapy implicates TNF-α as a key inflammatory mediator for periodontitis in both smokers and non-smokers." (PMID 38627806, 2024). "However, non-surgical therapy of periodontitis did not result in suppression of TNF levels in gingival crevicular fluid in one study, while another study reported that treatment of malocclusion secondary to periodontitis reduced the levels of TNF in gingival crevicular fluid and serum at 6 months." (PMID 39253090, 2024). "Infliximab improved BPO, PD, and CAL, as well as TNF-α in GCF in patients affected by RA and periodontitis, compared with RA patients treated without infliximab and healthy controls." (PMID 38139057, 2023). "Lastly, the biomarkers such as TNF-α and IL-1β, which are targeted by FGF21 and involved in periodontitis development, were not determined in the present study." (PMID 36474191, 2022). "This study evaluated the gene expression of IL-1ß, IL-6, TNF-α, MMP-1, MMP-2, MMP-8, MMP-9, TIMP-1, and TIMP-2 in the gingival tissue of individuals with periodontitis or peri-implantitis compared to individuals without periodontal or peri-implant disease." (PMID 33291232, 2020). "tested the effect of the use of TNF inhibitors (IFX, ETN, and ADA) in RA patients with and without periodontitis." (PMID 33193432, 2020).
periodontitis (continued). "Increased methylation of the TNF promoter region and decreased IL6 promoter methylation have been observed in the peripheral blood from patients with periodontitis, though the latter observation has not been confirmed in an independent study." (PMID 33256844, 2020). "We aimed to determine the levels of visfatin, interleukin-6 (IL-6) and tumor necrosis factor-alpha (TNF-α) in gingival crevicular fluid (GCF) in both obese/non-obese patients, with/without generalized chronic periodontitis (GCP)." (PMID 31365708, 2019). "We observed that the UWS concentration of IL-6 and TNF-α was not significantly different between T2DM and healthy individuals with no periodontitis." (PMID 29487749, 2018). "Cluster 1 contained 15 genes showing a positive correlation with TNFα and negative correlation with MMP9, primarily in the periodontitis tissues." (PMID 27486459, 2016). "The results of the present study showed that FUCO administration did not have a significant effect on serum TNF-α, IL-1β, or IL-6 levels or local OPG activity, which increased significantly in rats with periodontitis." (PMID 27043583, 2016). "The results indicating a decrease in the levels of the proinflammatory cytokines, IL-1α, -1β and -6, but not IL-10 or TNF-α, in the GCF of patients with chronic periodontitis, confirm the observations of previous studies." (PMID 24944641, 2014). "Thus, our novel finding that JNK is partly involved in the regulation of TNFα-induced mPGES-1 expression, which in concert with COX-2 regulates PGE2 production in gingival fibroblasts, indicates that this signal pathway may also be of importance in the pathogenesis of periodontitis." (PMID 20398340, 2010). "The periodontium of rats submitted to experimental periodontitis and received no treatment (EPD) showed marked immune-staining for both TNF- α and iNOS when compared to the periodontium of the sham group (respectively)." (PMID 20546603, 2010). "However, data yielded by human studies are presently inconsistent, as the circulating levels of CRP, TNF-α, and IL-6 are found to be elevated in T2DM patients with periodontitis in some cases, but not in others." (PMID 39337292, 2024). "Periodontitis induced by heat-killed Pg did not further increase the total bacterial load but led to increased gene expression levels of MCP-1, TNF-α, and IL-1β in the gums of AD mice and CRP levels in the plasma." (PMID 36915108, 2023). "The anti-inflammatory function of TNF-α in patients without periodontitis may also explain the negative correlation between BOP (%) and TNF-α in G3 (OSA) (rs = −0.543; p < 0.05)." (PMID 36967976, 2023). "TNF-α levels in saliva and serum were not significantly different between patients with periodontitis and healthy patients; in fact, TNF-α levels were lower in periodontitis patients." (PMID 36967976, 2023). "TNF-α enhances the expression of IL-1β, IL-6, and RANKL; however, its level in the gingival crevicular fluid (GCF) does not considerably differ before and after periodontitis treatment." (PMID 38002398, 2023). "However, plasma IL-1β, tumour necrosis factor-alpha (TNF-α), and metalloproteinase 8 (MMP-8) levels were not altered significantly by the induction of periodontitis or propolis treatment." (PMID 34070497, 2021). "It is important to note the discrepancies between the reports: in the case of IFNG, IL6, IL8, TNF, and TLR2, the differences in promoter methylation between patients with periodontitis and healthy individuals observed in some studies have not been reproduced in independent analyses." (PMID 33256844, 2020). "We show here that Porphyromonas gingivalis, one of the major pathogens in periodontitis, directly promotes osteoclastogenesis from RANKL-primed RAW-D (subclone of RAW264) mouse macrophages, and we show that TNF-α is not involved in the stimulatory effect on osteoclastogenesis." (PMID 22723864, 2012).